EGFR (epidermal growth factor receptor)
Diseases named in the same sentence as EGFR in open-access papers (continued):
Sharing a sentence is not in itself a finding about the gene and the disease.
lung cancer (continued). "Given the evidence linking L792H and L792F mutations to osimertinib resistance, the Guardant360 clinical genomic cfDNA database of EGFR-mutant lung cancer samples from 10/14/2015 through 2/4/2019 was retrospectively analyzed to investigate the prevalence of these alterations." (PMID 31632838, 2019). "The hippo signaling pathway effector YES-associated protein (YAP) has been found to promote resistance to MEK and RAF inhibition in non-small cell lung cancer, while TNKS activity protected lung cancer cells from Epidermal Growth Factor Receptor (EGFR) inhibition." (PMID 30717152, 2019). "Therefore, novel therapeutic strategies after resistance to EGFR inhibitors are still needed to improve the prognosis of patients with EGFR‐driven lung cancers." (PMID 30790471, 2019). "Moreover, the spliced RNA surrogate signatures of platelets were also found to be associated with the tumor tissue molecular subtype, such as EGFR and KRAS mutations in lung cancer and HER2 and MET amplifications in BC with 85–95% accuracy rates, respectively." (PMID 31705785, 2019). "Additionally, NO-donating drugs, such as aspirin, have been shown to suppress tumorigenesis of several types of tumors, including lung cancer in vitro and in vivo through modulating EGFR signaling." (PMID 31533363, 2019). "Females with lung cancer are more likely than males to be never-smokers, have adenocarcinoma with an activating EGFR or ALK mutation, which increase the risk of distant metastasis." (PMID 31822734, 2019). "The analysis of p22phox in lung carcinoma tissues could provide new insights into the selection of chemotherapy for the patients with EGFR-TKI resistant LUAD." (PMID 30800222, 2019). "For example, a novel lung cancer drug, osimertinib, has been intentionally developed to target non-small cell lung cancers, which progress after TKI therapy via acquisition of T790M mutation in EGFR gene." (PMID 30211169, 2018). "However, in lung cancer, the success of EGFR-targeted TKIs was achieved due to the antitumor activity in tumors harboring activating mutations in tyrosine kinase domain." (PMID 30007403, 2018). "By virtue of its sponge-like adsorptive activity, CDR1as may participate in the regulation of miR-7/EGFR and thus be involved in the development and progression of lung cancers." (PMID 30400981, 2018). "Additionally, EGFR inhibitors have been shown to be more effective in GPRC5A knockout lung cancer cells than in GPRC5A wild-type lung cancer cells, indicating that they are more suitable for lung cancer patients with lower GPRC5A expression." (PMID 30417009, 2018). "Preclinical research suggests that cross-talk between ARs and the epidermal growth factor receptor may enable androgen-induced proliferation of lung cancer cells by activating mitogen activated protein kinase-dependent pathways." (PMID 30121970, 2018). "Alpha2,6-sialylation of EGFR could prevent its dimerization and activation as it was shown that sialidase increased EGFR dimer formation upon EGF treatment in lung cancer cells." (PMID 29416702, 2018). "EGF induced various rates of EGFR endocytic degradation in lung cancer cells." (PMID 29976202, 2018). "NUFS‐sErt and NUFS technology may thus serve as new treatment strategies in EGFR‐mutant lung cancer patients with CNS failure and help to resolve some of the drug delivery issues with conventional EGFR‐TKIs." (PMID 30350450, 2018). "Thus, despite enormous advances in the therapeutic targeting of EGFR, further progress will be needed to achieve effective control or eradication of EGFR-mutant lung cancer." (PMID 30590030, 2018). "When lung cancer is exposed to targeted therapies, such as epidermal growth factor receptor (EGFR) inhibitor, adenocarcinoma cells can switch from EGFR dependent to EGFR independent with expression of neuroendocrine lineage markers, or to cells that lack all EGFR expression." (PMID 29911070, 2018).
lung cancer (continued). "Although gefitinib, an EGFR Tyr kinase inhibitor (TKI), was used to treat NSCLC patients 13 years ago, highly metastatic properties and drug resistance during TKI therapy still cause poor prognoses of lung cancer patients." (PMID 29548337, 2018). "In our own studies, expression array and RNAseq experiments reveal broad and marked induction of IFN-stimulated genes including CXCL10 in HNSCC cell lines and EGFR mutant lung cancer cell lines treated with EGFR inhibitors as well as EML4-ALK-driven cell lines treated with crizotinib." (PMID 29458371, 2018). "Point mutations of the codon for G719 account for about 3% of all EGFR mutations in lung cancer; are more common among non-smokers, females, and East Asians; and predict sensitivity to EGFR tyrosine kinase inhibitors." (PMID 29415746, 2018). "As AR is essential for the development of prostate cancer, and EGFR is a key factor for definite lung cancer, future research will be indispensable to pay attention to the stratification of patients before the application of Hsp90-Cdc37-client protein targeted therapy." (PMID 29699578, 2018). "Targeting the EGFR is a strategy for lung cancer treatment and prevention." (PMID 29548337, 2018). "Similar relations have also been show for EGFR in lung cancer." (PMID 29856777, 2018). "Epidermal growth factor receptor is a well‐validated target for lung cancer therapy." (PMID 29532998, 2018). "As hypoxia could induce resistance to EGFR-TKIs in EGFR-mutant lung cancer, we speculate cavity formation may impair the therapeutic response to EGFR-TKIs in EGFR-mutant ADC patients." (PMID 30352571, 2018). "In addition, the relationships between EGFR SNPs and clinical factors of lung cancer such as clinical prognosis, stage, and metastatic status were not examined." (PMID 30011810, 2018). "This study was performed to investigate whether miR‐1‐3p and miR‐206 increased the sensitivity of HGF‐induced gefitinib resistance in EGFR mutant lung cancer cells." (PMID 29664235, 2018). "Smoking is known to induce EGFR, and exhibit resistance to lung cancer treatment." (PMID 30289952, 2018). "In addition, the combination of afatinib and cetuximab for EGFR-mutant lung cancers with acquired resistance to gefitinib or erlotinib is clinically effective regardless of patients with T790M mutant or not." (PMID 29765556, 2018). "To further investigate the mechanism underlying the effect of NEDD4 on EGF-stimulated lung cancer cell migration, we first examined whether NEDD4 is in the EGFR signaling complex." (PMID 29455656, 2018). "To explore the mechanism of resistance to naquotinib, we established multiple naquotinib-resistant lung cancer cell lines from EGFR-TKI-naïve or EGFR-TKI pre-exposed resistant cells, and we performed a comprehensive analysis, which included next-generation sequencing." (PMID 29386539, 2018). "Positive results for Tu212 SCCHN cells and H292 lung cancer cells (high EGFR expression), DA-MB-231 breast cancer cells (moderate EGFR expression), and H460 lung cancer cells (low EGFR expression) showed that even with a variation in expression, the system detected the cell’s existence." (PMID 30569241, 2018). "Lung cancer A549 or H358 cells were stimulated with EGFR for 0–4 h." (PMID 29455656, 2018). "Furthermore, EGFR overexpression is a marker showing a poor prognosis in lung cancer and other cancer types." (PMID 30011810, 2018). "PRI-724, a more potent second-generation derivative of ICG-001 is currently in phase II clinical trials in other indications and could be combined with erlotinib or later generation EGFR TKIs in clinical trials for lung cancer." (PMID 30097569, 2018). "Furthermore, it is reported that the DOR can induce phosphorylation of the EGFR in lung cancer, leading to downstream ERK phosphorylation." (PMID 29374140, 2018). "Therefore, overcoming resistance of the drug-tolerant cell subpopulation is critical for elimination of EGFR-mutant lung cancer." (PMID 30291293, 2018).
lung cancer (continued). "Therefore, targeting EGF/EGFR signaling pathway to attenuate cancer cell tumorigenesis is the strategy for preventing and/or improving lung cancer patient prognosis." (PMID 29681982, 2018). "Thus, it is likely that NEDD4 mediates the EGFR cell migration signaling in lung cancer cell lines through activation of the lysosomal cathepsin B secretion pathway." (PMID 29455656, 2018). "Moreover, Metformin has been shown to be able to overcome drug resistance to tyrosine kinase inhibitors (TKI) of EGF receptor (EGFR) in lung cancer." (PMID 29723215, 2018). "Approximately 80% of the exosomes isolated from lung cancer biopsies contain epidermal growth factor receptor (EGFR) which has the potential to induce tolerogenic DC and regulatory T-cells, ultimately leading to the suppression of tumor antigen-specific CD8+ cells." (PMID 29720982, 2018). "The ability to detect tumor EGFR expression (based on the degree of tumor CT enhancement) could be extremely useful in discriminating between benign and malignant lung tumors on CT exam." (PMID 30408128, 2018). "We explored here whether the expression of RBD-mutant p110α might affect the activation of RAC1, as measured by guanosine triphosphate (GTP) loading, upon EGF stimulation in EGFR-mutant human lung cancer cell lines." (PMID 30590030, 2018). "Furthermore, the inhibition of the EGF signaling by EGFR small interfering RNA (siRNA), anti-EGFR antibody (cetuximab), and EGFR-TKi (Iressa) determined an increase in the sensitivity to RET inhibitors in lung cancer cells carrying CCDC6-RET fusion." (PMID 29455670, 2018). "In contrast, regarding KRAS oncogene, although the KRAS-MAPK pathway is downstream of EGFR signaling, KRAS-mutation driven lung cancers, which are mainly adenocarcinomas, do not respond to EGFR tyrosine kinase inhibitors (TKIs)." (PMID 29455666, 2018). "Additionally, EGF-induced PI3K/Akt and ERK activation was inhibited by propolin C in EGFR wild-type A549 lung cancer cells." (PMID 29681982, 2018). "It has been identified as an important drug target and understanding this gene has led to the development of multiple anti-cancer therapeutics (known as ‘EGFR inhibitors’) such as gefitinib, erlotinib, afatinib, brigatinib and icotinib for lung cancer, and cetuximab for colon cancer." (PMID 29351810, 2018). "However, most patients with EGFR-mutant lung cancer eventually develop acquired resistance to EGFR TKIs." (PMID 29875309, 2018). "Interestingly, the activation of CCDC6-RET has been identified in post progression samples of lung cancer patients, which developed resistance to EGFR TKIs." (PMID 29455670, 2018). "The antitumour efficacy of tyrosine kinase inhibitors (TKIs) in lung cancer patients with compound epidermal growth factor receptor (EGFR) mutations has not been resolved." (PMID 30055651, 2018). "An interaction between the ER and EGFR has been demonstrated in lung cancer cells." (PMID 30356721, 2018). "Changes of T790M in serum/plasma in EGFR-mutant lung cancer patients with T790M-AR might be a useful marker of symptomatic and radiographic outcome to osimertinib." (PMID 29930751, 2018). "In lung cancer, the EGFR pathway is the main signaling pathway." (PMID 30410721, 2018). "In addition, we have provided evidence that total TAMs were correlated to treatment response of EGFR-TKI in EGFR unselected advanced lung cancer patients." (PMID 29484139, 2018). "Additionally, BRAF, known as a member of RAS signaling pathway genes, was reported to be involved in pro-mitogenic activity and acquired resistance to EGFR TKIs in lung cancer and colorectal cancer through activating the MAPK signaling axis." (PMID 29455669, 2018). "Afatinib, a TKI targeting both EGFR and ErbB2, in combined with anti-EGFR antibody could remarkably attenuate the ErbB2 signaling and in turn resumed the sensitivity of lung cancer and colorectal cancer to TKIs in vitro and in vivo." (PMID 29455669, 2018).
lung cancer (continued). "Moreover, reversing EGF-induced migration and invasion and EMT changes were observed in propolin C-treated EGFR wild-type A549 lung cancer cells." (PMID 29681982, 2018). "Among 6 patients with grade IV hepatotoxicity, two-third of patients had pancreatic cancer, and the remaining 2 lung cancer patients had EGFR mutation, although there was no statistically significant factor." (PMID 30326853, 2018). "Despite the advances in therapeutic options such as targeted therapy using EGFR‐TKIs, the mortality rate for lung cancer still remains among the highest of cancer‐related deaths and this is largely attributed to the development of acquired resistance to EGFR‐TKIs." (PMID 29449326, 2018). "Interestingly, the drug trifluoroperazine hydrochloride, which inhibits the FOXO1 nuclear export, restored sensitivity of EGFR TK resistant lung cancer cells in vitro and in vivo." (PMID 30060526, 2018). "In contrast, the H1299 lung cancer cells strongly expressed EGFR." (PMID 30389917, 2018). "Knockdown of NEDD4 significantly reduces EGFR-promoted lung cancer cell migration rate." (PMID 29455656, 2018). "Moreover, resistance to anti-EGFR drugs in lung cancer is often related to the activation of Hedgehog signaling cascades." (PMID 30305811, 2018). "Additionally, EGFR ligation and signaling can promote integrin gene expression to regulate subsequent EGF-EGFR signaling, and extensive crosstalk is reported to occur between EGFR and integrin β1 in breast and lung cancers." (PMID 29515334, 2018). "This resistance may be related to MET–EGFR crosstalk, which was reported to be involved in therapeutic resistance to EGFR inhibitors in colon and lung cancers." (PMID 30227653, 2018). "Searching biological active phytochemicals to repress EGFR-regulated EMT might prevent lung cancer progression." (PMID 29681982, 2018). "The best characterized driver mutations for lung cancer are KRAS, EGFR, ALK, ROS1, BRAF, and MET." (PMID 29734788, 2018). "Epidermal Growth Factor Receptor (EGFR), one of growth factor signaling receptors, located in cholesterol-rich domains in the membrane, was associated with lipid-raft and involved in lung cancer." (PMID 30522496, 2018). "Further studies in vivo showed that three unique peptides of EGFR could stimulate anti-lung cancer immune responses in both wild-type mice and NUDE mouse tumor model." (PMID 30400835, 2018). "For example, rs712829 polymorphism has been shown to influence the response to EGFR-TKIs therapy in Chinese and Korean lung cancer patients while a lack of association was reported in the Japanese population." (PMID 30011810, 2018). "EGFR-dependent cell migration plays an important role in lung cancer progression." (PMID 29455656, 2018). "We used HEK293 cells and the EGFR-mutant lung cancer cell line, PC9." (PMID 30593278, 2018). "Guided treatments via molecular characterization of solid tumors using biomarkers such as immunohistochemistry (IHC) and genomic sequencing has resulted in better outcomes in subsets of patients, such as those with EGFR (epidermal growth factor receptor) mutant lung cancer and BRAF mutant melanoma." (PMID 29507702, 2018). "Therefore, understanding mechanisms between EGFR signaling pathways and oxidative stress-promoted lung tumorigenesis is necessary for lung cancer treatment and/or prevention." (PMID 29548337, 2018). "HGF has been shown to highly express in EGFR-TKI resistant lung cancer patients." (PMID 29455663, 2018). "One of the most important clinical problems in lung cancer therapy is to improve the therapeutic strategy for patients with lung adenocarcinoma who develop epidermal growth factor receptor–tyrosine kinase inhibitor (EGFR-TKI) resistance." (PMID 29463039, 2018).
lung cancer (continued). "For examples, either DZNep or GSK126 administration promoted the anti-tumor effect of TopoII inhibitor doxorubicin against BRG1 and EGFR mutant lung cancer, suggesting an opportunity for combination of traditional chemotherapy medicines and EZH2 inhibitors in NSCLC." (PMID 30002791, 2018). "With regard to lung cancer, mutations in EGFR are more often detected from female, Asian, or non-smoker patients." (PMID 29976202, 2018). "It is known that EGFR-tyrosine kinase inhibitor (TKI) therapy can significantly improve the treatment outcomes of patients with lung cancers who harbor EGFR mutations; moreover, this therapy has also been found to benefit some lung cancer patients with wild-type EGFR." (PMID 29970127, 2018). "Plasma beta-arrestin-1 levels were considerably higher in lung cancer patients than in healthy donors and were higher in patients who later experienced a progressive disease than in patients showing complete/partial response following EGFR inhibitor therapy." (PMID 30078843, 2018). "As EGFR mutant lung cancer patients survive longer because of the use of EGFR-TKIs, it would be unclear whether EGFR mutant lung cancer patients have BM due to their longer observation period or because EGFR mutant cancer cells tend to invade the brain." (PMID 29447182, 2018). "Our findings open a new hypothesis that low plasma beta-arrestin-1 concentrations in lung cancer patients might predict favourable responses to subsequent EGFR inhibitor therapy." (PMID 30078843, 2018). "While therapeutic targeting of mutant KRAS remains a significant challenge, the successful use of tyrosine kinase inhibitors (TKIs) for the treatment of patients with EGFR mutant tumors has dramatically altered the management and direction of lung cancer treatment." (PMID 29455675, 2018). "Additionally, osimertinib exhibited a certain effect in clinical lung cancers treated with other 3rd-gen EGFR-TKIs, such as rociletinib and nazartinib." (PMID 29386539, 2018). "For instance, high concentrations of serum hRNase5/ANG have been observed in patients who suffer from various cancer types, such as colorectal cancer, lung cancer, and acute myelogenous leukemia, in which EGFR has been well studied to be a therapeutic target in clinical practice." (PMID 30449278, 2018). "Because we previously demonstrated that EGFR may contribute to the formation of cancer stem-like tumorspheres in lung cancers, we assumed that EGFR may also contribute to cancer stemness in CRCs." (PMID 30068339, 2018). "Our study suggests that the inhibition of cMet, FGFR, or non-EGFR receptor tyrosine kinases (RTK) may potentiate the inhibitory effect of erlotinib in NSCLC with a higher EGFR expression, especially for acquired erlotinib-resistant lung cancer." (PMID 29449529, 2018). "Targeting PEAK1-mediated molecular mechanisms might be an effective therapeutic strategy for EGFR-TKI-based treatments in certain lung cancer subsets." (PMID 30038287, 2018). "The results showed a lack of association between rs712830 and rs11543848 of the EGFR gene and lung cancer." (PMID 30011810, 2018). "Interestingly, PTEN depletion contributed to erlotinib resistance in epidermal growth factor receptor (EGFR)-mutant lung cancer, suggesting a novel resistance mechanism." (PMID 29588850, 2018). "In addition to standard therapeutic strategies of lung cancers including surgery, chemotherapy, and radiotherapy, the molecular therapy targeting the epidermal growth factor receptor (EGFR) transmembrane glycoprotein has been developed in recent decades." (PMID 29856819, 2018). "As such, studies have shown that c-Met might be an effective therapeutic target for overcoming EGFR inhibitor resistance in lung cancer." (PMID 29455668, 2018). "Indeed, we detected higher beta-arrestin-1 plasma concentrations in lung cancer patients who later developed disease progression after EGFR inhibitor treatment." (PMID 30078843, 2018).